CD14 (CD14 molecule)
Diseases named in the same sentence as CD14 in open-access papers (continued):
Sharing a sentence is not in itself a finding about the gene and the disease.
asthma (continued). "This study is important because it is the first to evaluate together with the effects of both CD14 and TLR4 genetic variants on disease in adult patients with asthma in Turkey." (PMID 24524443, 2014). "A statistically significant correlation between CD14 genotypes and total IgE levels and severity of asthma was found in our atopic patients." (PMID 24524443, 2014). "In the present study, we investigated the effects of genetic variants of the CD14(C-159 T) and TLR4 (Asp299Gly and Thr399Ile) polymorphisms on adult asthma phenotypes specifically the severity of disease, total IgE concentrations and eosinophil counts." (PMID 24524443, 2014). "In this systematic review we summarize research on CD14 and TLRs in relation to asthma in Caucasian children." (PMID 23496969, 2013). "Future studies should include haplotype analysis and take environmental factors into account to further clarify the role of CD14 and toll-like receptors on childhood asthma." (PMID 23496969, 2013). "Further, we analyzed the effect of environmental factors on the relation between CD14 and TLRs and asthma in Caucasian children." (PMID 23496969, 2013). "It was reported that human monocytic cells are altered in the peripheral blood of patients with allergies and severe asthma leading to a selective expansion of intermediate CD14+CD16+ subset." (PMID 24358127, 2013). "Since CD14 and TLRs are the first mediators in the response of the innate immune system, it is plausible that their contribution to asthma development is influenced by environmental conditions." (PMID 23496969, 2013). "The aim of this study was to estimate the combined likelihood of developing asthma given the CD14 -260C>T genotype." (PMID 21745379, 2011). "This study evaluated 8 of these genes (IL4, IL13, TNF-α, HLA-DRB1, HLA-DQB1, FCER1B/MS4A2, CD14, ADAM33) as well as 3 glutathione-s-transferase genes (GSTM1, GSTP1, and GSTT1) for association with asthma/allergy among urban-residing African Americans." (PMID 21320344, 2011). "Both annexin and resistin show a self-reinforce trend in the CD14+ monocytes of asthma patients." (PMID 41550933, 2025). "Excluding heterogeneity and pleiotropy, MR analysis identified 13 ICTs (CD14 on CD33br HLA DR+ CD14dim, etc.)and asthma causality, and no reverse causality was observed." (PMID 40551049, 2025). "A recent systematic-review has highlighted the apparent modification of the effect of early life endotoxin exposure on risk of asthma in childhood, but not in adults, by the CD14/260 polymorphism." (PMID 31921716, 2019). "In previous publications we suggested that “% of CD4+CRTh2+T cells” and “% of CD14++CD16+PAR-2+ monocytes” may be good biomarkers of asthma severity." (PMID 31168305, 2019). "Asthma phenotypes based on age-of-onset may be differently influenced by the interaction between variation in toll-like receptor (TLR)/CD14 genes and environmental microbes." (PMID 28262750, 2017). "Thus, alterations of CD14 expression appear to be important in asthma, and is likely to be regulated, at least partially, at the gene level." (PMID 29937881, 2017). "We did not observe any association between TLR2, TLR4 or CD14 SNPs and asthma onset, nor was there any modification of these relationships by childhood farm exposure/childhood rural environment." (PMID 28262750, 2017). "Our data suggest that PAR-2 -mediated activation of CD14++CD16+ monocytes may play a role in the pathogenesis of severe asthma." (PMID 26658828, 2015). "In addition, among the whole populations, subjects with a history of asthma exacerbations over the last year had higher percent of CD14++CD16+ PAR-2+ cells in peripheral blood compared to subjects without exacerbations." (PMID 26658828, 2015). "Finally, we showed that the % of CD14++CD16+PAR-2+ monocytes in peripheral blood were higher in those patients having asthma exacerbations over the last year compared to patients without exacerbations." (PMID 26658828, 2015).
asthma (continued). "Therefore, there is the possibility that PAR-2 expression on CD14++CD16+ cells are influenced either by ICS or by asthma exacerbations." (PMID 26658828, 2015). "The relationship of the CD14 C-159 T genotype with the severity of asthma was also investigated." (PMID 24524443, 2014). "Furthermore, we found that the expression of some molecules such as CD14, TLR5, TLR6, TLR8, TREM-1, but also IRAK-1 and IRAK-2 genes was significantly negatively associated with total serum IgE, atopic sensitization, or asthma." (PMID 24603716, 2014). "The correlation of CD14 C-159 T genotype with the eosinophil count in asthma was also investigated." (PMID 24524443, 2014). "Consequently, our insight into the role of CD14 and TLRs in relation to asthma would benefit from haplotype analysis." (PMID 23496969, 2013). "Finally, we demonstrated that the subset of human intermediate CD14+CD16+ monocytes, which is associated with asthma progression and allergic inflammation, expressed high levels of miR-124." (PMID 24358127, 2013). "The evidence for a relation of CD14 with childhood asthma is limited." (PMID 23496969, 2013). "In many pathologies frequently occurring in urban environments, such as asthma, microbial infection and arthritis, there is a reported increase in the CD14++CD16+ and CD14+CD16++ subsets, which may be indicative of an activated immune system." (PMID 23557598, 2013). "On the other hand, interactions of TLR2, CD14 genotype, with farm exposure, and/or endotoxin exposure may protect against the the development of asthma." (PMID 22272211, 2012). "Characteristics and genotype distributions of reviewed studies on CD14 -260 (-159) C>T and asthma." (PMID 21745379, 2011). "The present meta-analysis found a non-significant association between the CD14 -260C>T polymorphism and overall asthma." (PMID 21745379, 2011). "We also observed a positive association of CD14(-159C>T) with asthma (data not shown), an association that has also previously been observed." (PMID 16759385, 2006). "In addition, our group has previously shown changes associated with asthma in the serum levels of many of the proteins detected in urine, i.e., IGFALS, FCN2, HSPG2, CD26/DPP4, and CD14, and suggested their use as potential phenotype/severity biomarkers of this disease." (PMID 39858454, 2025). "The analyses of cell-cell communication further elucidate the contributory roles of dendritic cells and CD14+ monocytes in the development and heterogeneity of asthma, as they exhibit increased reception and transmission of annexin and resistin signals in the asthma group." (PMID 41550933, 2025). "Additionally, a study has shown that polymorphisms in the CSF-1R gene may be a marker of susceptibility to asthma, with a high expression of the CSF-1R in CD14+ monocytes and neutrophils in subjects with asthma compared to normal controls." (PMID 39457693, 2024). "Considering time of asthma onset extends the two-dimensional problem of gene-environment interactions to a three-dimensional problem, since identified gene-environment interactions seldom reproduce for childhood and adult asthma (e.g., endotoxin exposure and CD14/260 genotype)." (PMID 31921716, 2019). "Similar to the human CD14 molecule, its bovine counterpart might transmit signals elicited by endotoxin, and thereby have an effect on the development or prevention of allergy and asthma." (PMID 28858242, 2017). "As a result it is thought that the effect of the CD14 -159 genotype (CC, TT or CT) on the asthma phenotype (in terms of total IgE levels) may also vary and numerous studies have been conducted to investigate the relationship between CD14 variants and total IgE levels." (PMID 24524443, 2014). "Further classification excluding CD4+ T and CD8+ T cell types revealed a significant increase in CD14+ monocytes and a significant decrease in CD16+ monocytes among asthma patients compared with healthy controls." (PMID 41550933, 2025).
asthma (continued). "CD14+CD16+ monocytes (left) in asthma patients expressed similar baseline levels of FcεRI as that observed on CD14+CD16− monocytes (left) at baseline." (PMID 40697948, 2025). "A significant decrease was observed in the percentage of cells expressing CX3CR1 in the intermediate CD14++CD16+ subset in patients with mild (75 ± 4; p = 0.002) and moderate (78 ± 3; p = 0.004) asthma compared to healthy (88%) controls." (PMID 31700522, 2019). "We first examined the relationship of genotype and asthma at the individual SNP/gene level (TLR4, CD14, TIRAP, and TNFα)." (PMID 30140039, 2018). "IFN-λ2 was predominately expressed in the CD16+ cells and CD14+ cells in healthy control subjects (HC) but upregulated only in CD8+ cells of AR and in eosinophils of asthma." (PMID 27057098, 2016). "A previous report suggests that the numbers of CD14++CD16+ monocytes are increased in patients with severe asthma compared to patients with mild and those with moderate asthma." (PMID 26658828, 2015). "Receiver operating characteristics (ROC) curve analysis showed that the percent of CD14++CD16+PAR-2+ in peripheral blood was able to discriminate between patients with severe and those with mild/moderate asthma with high sensitivity and specificity." (PMID 26658828, 2015). "There was higher percentage of CD14++CD16+PAR-2+ cells (0.25±0.03 vs 0.11±0.03, P = 0.006) in peripheral blood of asthmatics with asthma exacerbations compared to the rest of the population." (PMID 26658828, 2015). "We further analyzed our data to better understand the relationship between numbers of CD14++CD16+PAR2+ cells and asthma severity." (PMID 26658828, 2015). "Relations between CD14 C-159 T, TLR4 299 and TLR4 399 genotypes and duration of asthma history of allergic rhinitis-dermatitis, total IgE, eosinophil, skin prick test, forced expiratory volume 1 (FEV1) and severity of disease were evaluated." (PMID 24524443, 2014). "A signature containing CEACAM5 together with CD14 and TLR2 representing a response to bacterial infection has been described from an analysis of epithelial brushings and T‐cell transcriptomics from severe asthma patients." (PMID 35474304, 2022). "These need to be excluded from PMN quantification, either by SSC, as done here, or by the combination of CD14 vs. DH24A if FC was used for diagnosis of asthma based on PMN quantification without cytospin comparison." (PMID 35874777, 2022). "We previously identified dysregulated CD14+ monocyte responses after TLR activation in very young children with ASD, while other studies identified differences in monocyte responses after the stratification of groups by clinical measures of asthma/allergy." (PMID 35203983, 2022). "Notably, no statistically significant differential gene expression was detected when comparing other asthma cells or biopsies with control samples, including CD4+, CD8+, CD14+, CD15+, CD19+ cells, platelets (low expression), transverse colon or rectum biopsy." (PMID 34332619, 2021). "Interestingly, increased peripheral blood‐derived fibrocyte CD14 expression following co‐culture is abrogated by IL‐4/IL‐13, which are expressed by mast cells present in the ASM in asthma." (PMID 33209301, 2020). "CX3CR1 expression was also lower, with a lower percentage of cells expressing CX3CR1 in the non-classical CD14+CD16++ subset in all patients with asthma and this was inversely related to the percentage of cells expressing CCR2." (PMID 31700522, 2019). "CX3CR1 MFI was also significantly decreased (p = 0.0146) on the non-classical CD14+CD16++ subset in patients with severe asthma compared to healthy control subjects." (PMID 31700522, 2019). "Our objective was to determine whether CD14, CD16, CCR2 and CX3CR1 on monocyte subsets are potential indicators of asthma severity." (PMID 31700522, 2019).
asthma (continued). "Our data showed that the expression level (MFI) of CD14 on the monocyte subsets was not significantly different in patients with mild, moderate and severe asthma compared to healthy controls." (PMID 31700522, 2019). "PAR-2 expression is increased on CD14++CD16+ monocytes in the peripheral blood of subjects with severe asthma and may be a biomarker of asthma severity." (PMID 26658828, 2015). "Subjects with severe asthma had higher PAR-2 expression on CD14++CD16+ monocytes (intermediate monocytes) and also higher percentage of CD14++CD16+PAR-2+ monocytes (intermediate monocytes expressing PAR-2) in blood compared to subjects with mild/moderate asthma." (PMID 26658828, 2015). "ROC curve analysis showed that the percent of CD14++CD16+PAR-2+ in peripheral blood was able to discriminate between patients with severe and those with mild/moderate asthma with high sensitivity and specificity (AUC = 0.774, P = 0.008, 95% CI, sensitivity of 83.3% and specificity of 79.2%)." (PMID 26658828, 2015). "Since the function of CD14++CD16+ monocytes in asthma or other chronic inflammatory conditions is not known, the clinical significance of our observation of increased PAR-2 expression on CD14++CD16+ monocytes of patients with severe asthma is unclear." (PMID 26658828, 2015). "Consistent with this is a previous study in chronic persistent severe asthma (n = 9) which demonstrated increased mRNA expression of the innate immune receptors TLR2, TLR4 and CD14, as well as the cytokines IL-8 and IL-1β in induced sputum from patients with neutrophilic asthma." (PMID 24955983, 2014). "In conclusion, there is no convincing evidence yet for a role of CD14 and toll-like receptors in relation to childhood asthma." (PMID 23496969, 2013). "It was reported that this intermediate CD14+CD16+ subset (same subset is also referred to as CD14++CD16+ or CD14highCD16+) was expanded in patients with allergies and asthma and expressed a number of M2 surface markers such as CD163, CX3CR1, IL-4R, TGF-β1 and IL-10." (PMID 24358127, 2013). "All studies taken together, no clear role for CD14 and TLRs in childhood asthma can be determined based on this review." (PMID 23496969, 2013). "Before the advent of genome-wide association studies (GWAS), ADAM33, ADRB2, CD14, MS4A2 (alias FCER1B), IL13, IL4, IL4R, and TNF constituted the most replicated non-HLA candidate genes with asthma and related traits." (PMID 24039878, 2013). "The expression levels of HLA-DR proteins on blood CD14+CD163+ M2a monocytes were significantly elevated in the COPD-only group (7695 ± 3743 MFI) compared to the HS group (5391 ± 3153 MFI, adjusted p = 0.026) and the asthma group (4716 ± 1679 MFI, adjusted p = 0.012)." (PMID 41462706, 2025). "Monocytes are considered to play a role in the micro-inflammation of CKD and this could, at least in part, be attributed to a higher proportion of CD14++CD16+ cells in the monocyte population, as also observed in other inflammatory diseases such as asthma and rheumatoid arthritis." (PMID 31308443, 2019). "There was a significant decrease in CD16 MFI expression in patients with moderate and severe asthma in the intermediate (CD14++CD16+) monocyte subset and also in the non-classical (CD14+CD16++) subset in patients with severe asthma compared to healthy controls." (PMID 31700522, 2019). "Therefore, CD14 modulation could alter the TH2-differentiation and should be taken into account when studying asthma." (PMID 29515128, 2018). "Our study showed that subjects with severe asthma had higher percent of CD14++CD16+ cells expressing PAR-2 compared to patients with mild/moderate asthma, indicating that PAR-2-expressing CD14++CD16+ monocytes may be involved in the pathogenesis of severe asthma." (PMID 26658828, 2015).
asthma (continued). "Therefore, we concluded that moderate-to-severe asthma patients, compared to nonasthmatic control subjects, have increased percentages and numbers of total CD14+, CD14+CD16− (classical monocytes), CD14+CD16+ (intermediate monocytes), and CD14+CD2hi blood circulating monocytes." (PMID 40697948, 2025). "The percentage of monocytes expressing CCR2 in the intermediate CD14++CD16+ subset was significantly higher only in patients with mild (17 ± 4; p = 0.018) and moderate (17 ± 3; p = 0.003) asthma, not severe asthma, compared to healthy (7%) controls." (PMID 31700522, 2019). "The percentage of monocytes expressing CX3CR1 in the classical CD14++CD16− subset was not changed when patients with mild, moderate or severe asthma were compared with healthy controls." (PMID 31700522, 2019). "The percentage of monocytes expressing CCR2 in the classical CD14++CD16− subset was not changed when patients with mild, moderate or severe asthma were compared with healthy controls." (PMID 31700522, 2019). "In the non-classical CD14+CD16++ subset, the percentage of cells expressing CX3CR1 was significantly decreased in patients with mild (67 ± 4; p < 0.0001, moderate (74 ± 3.5; p = 0.003) or severe (74 ± 3.6; p = 0.003) asthma compared to healthy controls (85%)." (PMID 31700522, 2019). "Unlike “nonclassical” CD14+CD16++ monocytes, these cells selectively express CCR5 and are expanded in bacterial sepsis, dengue, Crohn's disease, rheumatoid arthritis, Eales’ disease, and asthma." (PMID 30150281, 2018). "In the non-classical CD14+CD16++ subset, the percentage of monocytes expressing CCR2 was significantly higher in the patients with mild (24 ± 3; p < 0.0001), moderate (16 ± 2.5; p = 0.009) and severe (18 ± 2.7; p = 0.002) asthma compared to healthy (9%) controls." (PMID 31700522, 2019).